ENSG00000200753
Synonyms: LOC124900239
Gene: Small nucleolar RNA gene on chromosome 7 (20,377,331 to 20,377,401, forward strand). Ensembl gene ENSG00000200753.
Gene Ontology:
Biological process: RNA processing
Cellular component: nucleolus
Homologues: Paralogues in human: SNORD56 (82% identical), SNORD56B (77% identical).